TRBV25-1 (T cell receptor beta variable 25-1)
Description:
V region of the variable domain of T cell receptor (TR) beta chain that participates in the antigen recognition. Alpha-beta T cell receptors are antigen specific receptors which are essential to the immune response and are present on the cell surface of T lymphocytes. Recognize peptide-major histocompatibility (MH) (pMH) complexes that are displayed by antigen presenting cells (APC), a prerequisite for efficient T cell adaptive immunity against pathogens. Binding of alpha-beta TR to pMH complex initiates TR-CD3 clustering on the cell surface and intracellular activation of LCK that phosphorylates the ITAM motifs of CD3G, CD3D, CD3E and CD247 enabling the recruitment of ZAP70. In turn ZAP70 phosphorylates LAT, which recruits numerous signaling molecules to form the LAT signalosome. The LAT signalosome propagates signal branching to three major signaling pathways, the calcium, the mitogen-activated protein kinase (MAPK) kinase and the nuclear factor NF-kappa-B (NF-kB) pathways, leading to the mobilization of transcription factors that are critical for gene expression and essential for T cell growth and differentiation. The T cell repertoire is generated in the thymus, by V-(D)-J rearrangement. This repertoire is then shaped by intrathymic selection events to generate a peripheral T cell pool of self-MH restricted, non-autoaggressive T cells. Post-thymic interaction of alpha-beta TR with the pMH complexes shapes TR structural and functional avidity.
Synonyms: TRBV251; TCRBV11S1A1T; TCRBV25S1
Gene: T-cell receptor variable (V) gene on chromosome 7 (142,670,740 to 142,671,244, forward strand). Ensembl gene ENSG00000282499.
Subcellular location: Cell membrane
Gene Ontology:
Biological process: cell surface receptor signaling pathway
Cellular component: plasma membrane
Homologues: Orthologues: chimpanzee TRBV25-1 (83% identical), pig TRBV25-1 (64% identical), dog TRBV25-1 (62% identical). Paralogues in human: TRBV10-3 (55% identical), TRBV10-1 (54% identical), TRBV28 (54% identical), TRBV24-1 (52% identical), TRBV27 (52% identical), TRBV6-7 (52% identical), TRBV10-2 (51% identical), TRBV6-1 (51% identical), TRBV6-2 (51% identical), TRBV6-4 (51% identical), TRBV6-5 (51% identical), TRBV6-6 (51% identical), and 39 more.
Diseases named in the same sentence as TRBV25-1 in open-access papers:
TRBV25-1 is named in the same sentence as 4 diseases in open-access papers, as found by Europe PMC text mining. Sharing a sentence is not in itself a finding about the gene and the disease. The quoted sentences say what the papers report.
breast tumor (1 paper, 2020). "The TRBV9-1, TRBV25-1, and TRBV28-1 genes of CDR3 repertoires in Mouse 1 breast tumor tissue and lung metastatic tissue were lost; and the TRBV9-1 gene of CDR3 repertoires in Mouse 2 breast tumor tissue and lung metastatic tissue was lost." (PMID 33029539, 2020).
tumor (1 paper, 2022). "This correlation is weaker when looking at the TRAV10 and TRBV25-1 genes together with the M2 signature genes in the tumor site (R = 0.63) and inexistent in the normal adjacent tissue (R = 0.064)." (PMID 35885028, 2022).
TRBV25-1 also shares sentences with these, for which no sentence is quoted: cancer (1 paper); colon adenocarcinoma (1).